IL34 (interleukin 34)
Diseases named in the same sentence as IL34 in open-access papers (continued):
Sharing a sentence is not in itself a finding about the gene and the disease.
breast cancer (continued). "Together with the observed low CSF-1R activation in breast cancer cells, we hypothesize that IL-34 and its receptor PTPRZ1 directly regulate cancer cells, whereas CSF-1/CSF-1R are primarily involved in regulation of stromal and immune cells." (PMID 29796177, 2018). "In breast cancer tumors abundant IL-34 expression variations were observed indicating that different gene expression patterns may exist in breast cancer tissues." (PMID 29796177, 2018). "Cytotoxic therapies have been shown to induce the production of IL-34 in breast cancer." (PMID 29796177, 2018). "We quantified relative IL-34 mRNA expression in primary tumor tissue samples of 75 patients by qRT-PCR and searched for correlations between IL-34 mRNA expression and clinical and histopathological characteristics of breast cancer patients." (PMID 29796177, 2018). "In this article, correlative analysis of IL-34 expression and breast cancer prognosis stratified by PAM50 tumor subtype showed an unexpected prognostic relationship between intrinsic subtype and overall survival that demonstrated patterns contrasting previous studies analyzing CSF-1 and CSF-1R." (PMID 29796177, 2018). "Furthermore, breast cancer cells are not only a source of CSF-1 as already described, but also a source for IL-34, the alternative ligand for the CSF-1R." (PMID 26098772, 2015). "Additionally, we analyzed a subset of primary breast cancer patients, and certain patients with brain metastasis of lung and breast cancer and found high CSF-1R, CSF-1 and/or IL-34 expression, respectively." (PMID 26098772, 2015). "Recently, DeNardo and coll reported that, in breast cancer, some antitumoral drugs induce the production of both IL-34 and M-CSF by mammary epithelial cells, suggesting that, in some circumstances, therapeutic strategies may favor tumor immune escape." (PMID 23409120, 2013). "In breast cancer, some antitumoral drugs induce the production of both IL-34 and M-CSF by mammary epithelial cells, which may favor the recruitment of Mφ into the tumor microenvironment." (PMID 23409120, 2013). "The alternative ligand IL-34 could be responsible for activating the CD115 pathway within mammary tumors." (PMID 24019914, 2013). "Remarkably, IL34-deficient breast cancer cells failed to establish tumors in the mouse cerebellum." (PMID 42166785, 2026). "Interestingly, several other HDAC1/7-SE upregulated targets, such as SNPH, CCANG4, PREX1, IGFBP5, IL34 and BCAS4 also demonstrate remarkable level of breast cancer associated over-expression, providing additional support for the relevance of the ET-125 signature." (PMID 36038558, 2022). "However, the role of IL-34 in breast cancer is still poorly understood." (PMID 33800170, 2021). "Next, we asked whether IL-34 expression could be detected in primary human breast cancers." (PMID 29796177, 2018). "However, the role of IL-34 in breast cancer is still ill-defined." (PMID 29796177, 2018). "To experimentally evaluate, whether IL-34 and CSF-1 directly regulate breast cancer cells depending on their subtype, we assessed the effect of recombinant IL-34 and CSF-1 on luminal-like MCF7, HER-2-positive SK-BR-3, and basal type MDA-MB-231 breast cancer cells." (PMID 29796177, 2018). "IL34, CSF1 and their receptors co-expressed within the immune cell infiltrated area and regulated the different downstream signalling pathways in breast cancer." (PMID 35967449, 2022). "Our study demonstrates the role of IL-34-induced MEK/ERK and JNK/c-Jun cascades in breast cancer and highlights the regulatory role of PIN1 in IL-34-induced breast tumorigenesis." (PMID 33800170, 2021). "IL-34 increased the phosphorylation of MEK1/2, ERK1/2, JNK1/2, and c-Jun through CSF1R in mouse skin epidermal JB6 C141 cells and human breast cancer MCF7 cells." (PMID 33800170, 2021). "In the present study, we demonstrated that IL-34-induced MEK/ERK and JNK/c-Jun signaling is regulated by PIN1 in breast cancer." (PMID 33800170, 2021).
breast cancer (continued). "When analyzed by Western blotting, we found no obvious difference in the strength of CSF-1R, ERK, and FAK activation between IL-34- and CSF-1-stimulated MCF-7 breast cancer cells." (PMID 29796177, 2018). "IL-34 expression was similar between luminal and HER2 cell lines, but showed IL-34 downregulation when compared to normal breast cancer cell lines." (PMID 29796177, 2018). "We used the ESTIMATE algorithm to correlate the extent of stromal cells with expression of IL-34, CSF-1, CSF-1R, PTPRZ1, and syndecan-1 in breast cancer tissue from the TCGA breast cancer dataset." (PMID 29796177, 2018). "After determining the involvement of IL-34 in the activation of MEK/ERK and JNK/c-Jun signaling cascades in JB6 Cl41 cells, we further confirmed whether IL-34 influences the MAPK pathway in breast cancer cells." (PMID 33800170, 2021). "IL-34 can inhibit the proliferation of glioblastoma cells, promote the differentiation of nonleukemia cells into monocyte-like cells, and inhibit the migration of HER2-positive breast cancer cells." (PMID 34336646, 2021). "Overall, our study highlights the previously unknown role of IL-34/CSF1R signaling in breast cancer and demonstrates the regulatory role of PIN1 in IL-34-induced tumorigenesis." (PMID 33800170, 2021). "Although IL-34 plays an important role in cancer development, the molecular mechanism of IL-34 in breast cancer development has not yet been taken into consideration." (PMID 33800170, 2021). "In particular, IL-34 promotes cancer cell migration in basal breast cancer cells through a mechanism that is independent of M-CSF1-R, while it inhibits cancer cell migration in HER2-positive cells." (PMID 31968663, 2020). "IL-34 promoted cancer cell migration in basal MDA-MB-231 breast cancer cells independent of the CSF-1R, while it reduced cancer cell migration in HER2-positive SK-BR-3 cells." (PMID 29796177, 2018). "Expression of IL-34 was associated with a favorable prognosis in luminal and HER2 but not basal breast cancer patients." (PMID 29796177, 2018). "In addition, IL-34 also has a protective role in some cancer, such as non-small cell lung cancer, colorectal cancer, breast cancer, and lung cancer, hematologic malignancies, and head and neck cancer." (PMID 36698935, 2022). "Thus, we assume that syndecan-1 and IL-34 do not act in concert to regulate macrophages in breast cancer." (PMID 29796177, 2018).
lung carcinoma (22 papers, 2015 to 2025). "A study demonstrated that high expression of IL-34 and M-CSF and their ligands was associated with lower survival in a cohort of lung cancer patients, because lung cancers with high IL-34 and M-CSF expression were more likely to progress to advanced stages." (PMID 39403370, 2024). "Next, we evaluated the association between IL-34 and M-CSF expression in lung cancers and the related impact on patients’ survival." (PMID 29323162, 2018). "In cancer, the expression of IL-34 has been suggested to associate with tumor growth, metastasis, angiogenesis, and therapeutic resistance such as in lung cancers and malignant pleural mesotheliomas." (PMID 29515691, 2018). "In cancer, the expression of IL-34 has been suggested to associate with tumor growth, metastasis, angiogenesis and importantly to therapeutic resistance such as in lung cancers and malignant pleural mesotheliomas." (PMID 29515691, 2018). "A total of 5 out of 40 tests (1 blood cancer, 1 brain cancer, 1 colorectal cancer and 2 lung cancer) revealed an association between IL-34 gene expression and cancer prognosis." (PMID 25395235, 2015). "Chemoresistant lung cancer cells secrete IL‐34, which is associated with immune suppression by inducing the M2‐like phenotype of TAMs,37 and co‐expression of IL‐34 and CSF‐1 in cancer cells is correlated with a worse clinical course in patients with lung cancer." (PMID 35132816, 2022). "Indeed, elevated levels of IL-34 have been associated with poor prognosis in primary lung cancer and such levels significantly correlate with the development of chemoresistance and progression in non-viral hepatocellular carcinoma and in basal breast cancer." (PMID 34535634, 2021). "Indeed, our data shown in this study indicates an association between high expression of IL-34 and M-CSF in cancer tissues with disease stages and poor survival in lung cancer patients." (PMID 29323162, 2018). "Together, these findings indicate an association between IL-34 and M-CSF expression with stages in lung cancers, and thus may serve as progression parameters." (PMID 29323162, 2018). "Furthermore, high expression of IL-34 and M-CSF associates with advanced stages of lung cancers." (PMID 29323162, 2018). "Consistently, studies in a humanized mouse model of lung cancer showed that IL-34-producing chemoresistant tumors exhibit increased numbers of M2-type TAMs and reduced frequencies of tumor-infiltrating cytotoxic CD8+ T cells." (PMID 36765929, 2023). "The same group transplanted human lung cancer tissue expressing both IL-34 and PD-L1 in immunologically humanized mice to determine the effect of IL-34 neutralization, along with the immune checkpoint blockade, in human tumors." (PMID 36765929, 2023). "In lung cancer, tumor cells express IL-34, which induced TAM polarization into an M2 pro-tumorigenic phenotype with the properties of chemoresistance to tumor cells through Akt signaling pathway activation." (PMID 33408768, 2021). "For example, a higher expression of IL-34 was found in lung cancer compared to normal lung tissues and this was correlated with a poor patients’ prognosis." (PMID 34535634, 2021). "Although lung cancer has a high fatality rate, and IL-34 plays an important role in tumors, there are few studies on IL-34 in lung cancer." (PMID 34336646, 2021). "It has been reported that IL‐34 contributes to the activation and progression of multiple cancers and is closely related to mortality in brain and lung cancers." (PMID 32573824, 2020). "More recent studies documented the overexpression of IL-34 in several cancers, such as hepatocarcinoma, osteosarcoma, multiple myeloma, colon cancer, and lung cancer, and showed that tumor cells can produce and functionally respond to this cytokine." (PMID 31968663, 2020).
lung carcinoma (continued). "A more pronounced expression of IL-34, together with high levels of M-CSF-1, was also seen in primary lung cancer tissues compared with normal lung tissues, where the elevated levels of the cytokine significantly correlate with poor prognosis." (PMID 31968663, 2020). "In this study, we also observed a co-expression of M-CSF and IL-34 in a sub-population of lung cancer patients, which correlates with poorer prognosis." (PMID 29323162, 2018). "Together, these results indicate a correlation between IL-34/M-CSF expression with poor survival and disease progression in lung cancer patients." (PMID 29323162, 2018). "Again, high expression of CSF1R correlates with poor survival in lung cancer patients, similar with IL-34 and M-CSF expression." (PMID 29323162, 2018). "Kaplan-Meier analysis of overall survival in lung cancer patients based on this classification showed that high expression of M-CSF or IL-34 correlates with poor survival compared to groups that showed weak or absent expression of the two ligands." (PMID 29323162, 2018). "Our data showed that single expression of M-CSF or IL-34 can be observed in primary lung cancer tissues and correlated with poor survival." (PMID 29323162, 2018). "Together, these results suggest that high co-expression of both IL-34 and M-CSF correlates with poorer survival in lung cancer patients." (PMID 29323162, 2018). "In this paper, we describe for the first time the clinicopathological relevance of M-CSF and IL-34 expression with disease stages and poor survival in a cohort of lung cancer patients." (PMID 29323162, 2018). "In the cohort of lung cancer patients described in this study, IL-34 and M-CSF were naturally expressed in cancer tissues prior to any therapeutic procedures." (PMID 29323162, 2018). "In this study, we show that IL-34 and M-CSF expression correlates with poor survival in a cohort of lung cancer patients." (PMID 29323162, 2018). "We tested seven representative lung cancer cell lines for the expression of CSF-1R and its ligands, CSF-1 and IL-34." (PMID 27486763, 2016). "Support for this hypothesis comes from studies in lung cancer showing that lung cancer cells exposed to chemotherapeutic agents exhibit enhanced NF-kB activation, which in turn sustains elevated production of IL-34 in chemoresistant cells." (PMID 36765929, 2023). "The expression of IL-34 and lung cancer progression is still under debate; some previous studies have reported that IL-34 overexpression is related to the poor survival and prognosis of patients with lung cancer." (PMID 36798830, 2023). "IL-34 is thought to mediate the induced survival of lung cancer cells, and hence may be disadvantageous to patients." (PMID 34336646, 2021). "In addition, IL-34 expression is enhanced in advanced stages of lung cancers and correlates with poor survival and disease progression in lung cancer patients." (PMID 33800170, 2021). "Interestingly, IL‐34 was found to be highly increased in patients with advanced stages of lung cancer compared with early stages." (PMID 32573824, 2020). "In lung cancers, IL-34 triggers activation of CCAAT/enhancer-binding protein β via AKT-mediated pathway with the downstream effect of enhancing the pro-tumorigenic and immunosuppressive functions of TAMs and consequently promoting the survival of chemoresistant cancer cells." (PMID 31968663, 2020). "Finally, we evaluated the expression level of IL-34 and M-CSF according to each stage in lung cancer patients." (PMID 29323162, 2018). "In conclusion, IL-34 and M-CSF may help to predict poor survival and tumor progression in lung cancer patients, which should be further evaluated in other cohorts of lung cancer patients and various cancers in future studies." (PMID 29323162, 2018). "However, IL-34 knockdown enhanced the susceptibility of CRC cells to oxalipaltin-induced death, in line with the demonstration that IL-34, produced during chemotherapy, increases lung cancer cell survival." (PMID 34535634, 2021).
lung carcinoma (continued). "Thus, evaluating the expression of both M-CSF and IL-34 may help to estimate disease progression and malignant degree in lung cancer patients." (PMID 29323162, 2018). "Indeed, the high expression of IL-34 and CSF-1 in lung cancer tissues is intimately related to the progression of lung cancer, which suggests that IL-34 and CSF-1 secreted by tumor cells may activate and maintain the pro-tumor function of TAMs by interacting with the CSF1R receptor on TAMs." (PMID 33224886, 2020). "Similar with IL-34 and M-CSF, immunohistochemical staining showed that CSF1R is expressed in lung cancer tissues with a variety among patients." (PMID 29323162, 2018). "Kaplan-Meier analysis of overall survival in lung cancer patients based on IL-34 and CD163 expression showed that patients with high expression of both IL-34 and CD163 have the poorest survival compared to other groups." (PMID 29323162, 2018). "Immunohistochemical staining of IL-34, M-CSF, CSF1R and CD163 was performed on lung cancer tissues obtained from patients by surgical resection." (PMID 29323162, 2018). "On the other hand, the absence of IL-34 staining in cancer tissues was frequently associated with the absence of M-CSF staining, and vice versa, which may suggest a reciprocal relationship between the expression of IL-34 and M-CSF in lung cancers." (PMID 29323162, 2018). "Next, we examined the relation between M-CSF or IL-34 with CD163 expression and its impact on survival in this cohort of lung cancer patients." (PMID 29323162, 2018). "As expected, 60% of cancer tissues that showed high expression of IL-34 were accompanied with high expression of CD163, and the absence of CD163 staining was frequently associated with negative staining of IL-34, which indeed suggests a correlation between IL-34 and CD163 expression in lung cancers." (PMID 29323162, 2018). "Among the two types of lung cancer, the lower expression of the IL-34 gene was related to poor survival and was found in non-small cell lung cancer (NSCLC) case (GSE8894)." (PMID 25395235, 2015). "Finally, the role of IL-34 in the occurrence and development of LUAD is not fully understood, especially since it exhibits different effects in early lung cancer and advanced lung cancer, which requires further research to explore the underlying mechanism." (PMID 34336646, 2021).
inflammatory bowel disease (20 papers, 2015 to 2025). A spectrum of small and large bowel inflammatory diseases of unknown etiology. "The expression of IL-34 increases with inflammation in patients with inflammatory bowel disease and experimental colitis and is associated with an elevated TNFα and IL-6 expression." (PMID 29472590, 2018). "Overexpression of IL-34 is associated with autoimmune diseases, such as RA, inflammatory bowel disease (IBD) and Sjogren's syndrome." (PMID 34422917, 2021). "This suggests that IL-34 participates in the crosstalk between the epithelium and immune system in inflammatory bowel diseases." (PMID 33408768, 2021). "IL-34 is also believed to be related to psoriasis, psoriatic arthritis, obesity, liver disease, kidney disease, and inflammatory bowel disease." (PMID 34095310, 2021). "Differential intestinal expression of the macrophage growth factors colony stimulating factor-1 (CSF-1), interleukin (IL)-34, and their shared CSF-1 receptor (CSF-1R) in inflammatory bowel disease (IBD) has been shown." (PMID 27898738, 2016). "Interleukin-34 (IL-34), a cytokine produced by a variety of immune and non-immune cells, is spontaneously produced in the human gut, and its expression is up-regulated in the inflamed gut of patients with inflammatory bowel disease (IBD) and in CRC tissue." (PMID 33260828, 2020). "The macrophage differentiation factor interleukin-34, produced by intestinal epithelial cells, is up-regulated in patients with inflammatory bowel disease, and may be a novel modulator of intestinal inflammation." (PMID 25896238, 2015). "Experimental evidence suggests that, in the inflamed gut of inflammatory bowel disease (IBD) patients, interleukin-34 (IL-34) triggers detrimental signaling pathways." (PMID 39451216, 2024). "In inflammatory bowel disease (IBD), IL-34 protects the integrity of the intestinal epithelium, and IL-34-differentiated macrophages show decreased IL-1β and TNF-α expression." (PMID 30405534, 2018). "High expression of IL-34 has been found to correlate with chronic inflammation and some autoimmune diseases such as Sjogren's syndrome (SS) and mucosa of inflammatory bowel disease (IBD)." (PMID 28659662, 2017). "IL-34 is constitutively expressed in the healthy human small intestine and colon and its production is markedly increased in damaged gut of patients with Crohn’s disease and patients with ulcerative colitis, the main forms of chronic inflammatory bowel diseases (IBD) in human beings." (PMID 35529879, 2022). "In some other reports, PTN was found not the only activation of PTPRZ1 pathway, inflammation and immune can also activate the PTPRZ1 pathway, such as interleukin (IL)-34, an important receptor of PTPRZ1, promotes the expression of PTPRZ1 in inflammatory bowel disease (IBD)." (PMID 30497491, 2018). "Zwicker and Xu reported that IL-34 might inhibit TNF-α expression in macrophages 1 and overlap with the anti-inflammatory cytokine IL-10-secreting macrophages in inflammatory bowel disease and infectious disease models, suggesting the anti-inflammatory potential of IL-34." (PMID 39883639, 2025). "PTPRZ1 involvement has been linked to various inflammatory diseases such as inflammatory bowel disease (IBD) and lupus nephritis, where PTPRZ1 expression was found to correlate with IL-34, CSF1, and CSF-1R expression." (PMID 36530919, 2022).